ADAM17 (ADAM metallopeptidase domain 17)
Description:
Transmembrane metalloprotease which mediates the ectodomain shedding of a myriad of transmembrane proteins including adhesion proteins, growth factor precursors and cytokines important for inflammation and immunity. Cleaves the membrane-bound precursor of TNF to its mature soluble form. Responsible for the proteolytical release of soluble JAM3 from endothelial cells surface. Responsible for the proteolytic release of several other cell-surface proteins, including p75 TNF-receptor, interleukin 1 receptor type II, p55 TNF-receptor, transforming growth factor-alpha, L-selectin, growth hormone receptor, MUC1 and the amyloid precursor protein. Acts as an activator of Notch pathway by mediating cleavage of Notch, generating the membrane-associated intermediate fragment called Notch extracellular truncation (NEXT). Plays a role in the proteolytic processing of ACE2. Plays a role in hemostasis through shedding of GP1BA, the platelet glycoprotein Ib alpha chain (By similarity). Mediates the proteolytic cleavage of LAG3, leading to release the secreted form of LAG3 (By similarity). Mediates the proteolytic cleavage of IL6R, leading to the release of secreted form of IL6R. Mediates the proteolytic cleavage and shedding of FCGR3A upon NK cell stimulation, a mechanism that allows for increased NK cell motility and detachment from opsonized target cells. Cleaves TREM2, resulting in shedding of the TREM2 ectodomain.
Synonyms: CD156b; CSVP; TACE; ADAM18; HYPT16; NISBD; NISBD1
Tractability: Small molecule: a drug acting on it is in phase 2 or 3 trials; a structure with a bound ligand is known; a high-quality ligand is known; it has a high-quality binding pocket; it belongs to a druggable protein family. Antibody: UniProt places it where antibodies can reach, with high confidence; its Gene Ontology location is reachable by antibodies, with high confidence; UniProt predicts a signal peptide or a membrane-spanning region. PROTAC: ubiquitination databases record sites on it; its protein half-life has been measured; a small molecule that binds it is known.
Target class: Metallo protease MAM clan; Metallo protease; Protease; Enzyme; Metallo protease M12B subfamily
Chemical probes: CHEMBL209970, JG26, PD081053, PD081073, PD081121, PD081207, PD081215, PD081279, PD081446, PD081644, PD081869, PD082019, PD082025, PD082069, PD082096, PD082102, PD082303, PD082307, PD082730, PD082963, and 12 more
Gene: Protein-coding gene on chromosome 2 (9,488,486 to 9,556,732, reverse strand). Ensembl gene ENSG00000151694.
Subcellular location: Cell membrane
Subcellular location (Human Protein Atlas): Cytosol
Pathways (Reactome):
Signal Transduction: Activated NOTCH1 Transmits Signal to the Nucleus; Nuclear signaling by ERBB4; Regulated proteolysis of p75NTR; Release of Hh-Np from the secreting cell; Signaling by EGFR; TNF signaling
Disease: CD163 mediating an anti-inflammatory response; Constitutive Signaling by NOTCH1 HD Domain Mutants; Constitutive Signaling by NOTCH1 HD+PEST Domain Mutants; Constitutive Signaling by NOTCH1 PEST Domain Mutants; Constitutive Signaling by NOTCH1 t(7;9)(NOTCH1:M1580_K2555) Translocation Mutant
Extracellular matrix organization: Collagen degradation
Immune System: Growth hormone receptor signaling
Gene Ontology:
Molecular function: cytokine binding; endopeptidase activity; integrin binding; interleukin-6 receptor binding; metalloendopeptidase activity; metallopeptidase activity; Notch binding; PDZ domain binding; protein binding; tumor necrosis factor binding; ubiquitin binding; peptidase activity; metallodipeptidase activity
Biological process: amyloid precursor protein catabolic process; cell adhesion; cell adhesion mediated by integrin; cellular response to high density lipoprotein particle stimulus; commissural neuron axon guidance; cytokine precursor processing; defense response to Gram-positive bacterium; epidermal growth factor receptor signaling pathway; membrane protein ectodomain proteolysis; negative regulation of transforming growth factor beta receptor signaling pathway; Notch receptor processing; phosphatidylinositol 3-kinase/protein kinase B signal transduction; positive regulation of blood vessel endothelial cell migration; positive regulation of cell growth; positive regulation of cell migration; positive regulation of cell population proliferation; positive regulation of chemokine production; positive regulation of epidermal growth factor receptor signaling pathway; positive regulation of G1/S transition of mitotic cell cycle; positive regulation of T cell chemotaxis; positive regulation of tumor necrosis factor production; positive regulation of tumor necrosis factor-mediated signaling pathway; positive regulation of vascular endothelial cell proliferation; protein processing; proteolysis; and 17 more
Cellular component: actin cytoskeleton; apical plasma membrane; cell surface; cell-cell junction; cytoplasm; focal adhesion; membrane; membrane raft; plasma membrane; ruffle membrane; endoplasmic reticulum lumen; Golgi membrane
Genetic constraint (gnomAD): Loss-of-function variants: 33 observed, 78.15 expected, observed/expected ratio (o/e) 0.42, 90% interval 0.32 to 0.56. The upper end of that interval is the gene's LOEUF score, 0.56, which puts it in group 2 of 6, group 1 being the genes least tolerant of losing a copy. Missense variants: 648 observed, 854.14 expected, observed/expected ratio (o/e) 0.76, 90% interval 0.71 to 0.81. Synonymous variants: 295 observed, 308.99 expected, observed/expected ratio (o/e) 0.95, 90% interval 0.87 to 1.05.
Gene-disease validity (ClinGen):
ClinGen rates the evidence that ADAM17 causes each of these diseases.
congenital heart disease (autosomal dominant): Limited. A heart disease that is present at birth.
Homologues: Orthologues: chimpanzee ADAM17 (99% identical), macaque ADAM17 (99% identical), rabbit ADAM17 (93% identical), rat Adam17 (92% identical), dog ADAM17 (92% identical), mouse Adam17 (92% identical), guinea pig ADAM17 (90% identical), pig ADAM17 (88% identical), tropical clawed frog adam17 (70% identical), zebrafish adam17b (61% identical), zebrafish adam17a (60% identical), Drosophila melanogaster Tace (36% identical), and 1 more. Paralogues in human: ADAM10 (22% identical), ADAM12 (21% identical), ADAM9 (20% identical), ADAM19 (20% identical), ADAM22 (20% identical), ADAM33 (20% identical), ADAM15 (19% identical), ADAM8 (19% identical), ADAM30 (18% identical), ADAM11 (18% identical), ADAM28 (18% identical), ADAM23 (18% identical), and 8 more.
Diseases named in the same sentence as ADAM17 in open-access papers:
ADAM17 is named in the same sentence as 357 diseases in open-access papers, as found by Europe PMC text mining. Sharing a sentence is not in itself a finding about the gene and the disease. The quoted sentences say what the papers report.
breast carcinoma (80 papers, 2007 to 2026). "Tissue expression of ADAM17 correlated with severe outcomes in mammary carcinoma patients and underlined its critical role in cancer." (PMID 39286024, 2024). "An earlier study indicated that breast cancer-associated fibroblasts stimulated breast cancer cell proliferation through ADAM17-mediated cleavage of TGF-α." (PMID 36466812, 2022). "It was found that downregulation of ADAM17 in activated platelets from breast cancer patients was associated with tumor metastasis and clinical stage of breast cancer." (PMID 36466812, 2022). "There was previously reported that TGFα elevated expression together with ADAM17 expression in breast cancer is associated with lymph node metastasis and worse survival prognosis." (PMID 35290621, 2022). "High ADAM17 expression was also associated with increased lymph node involvement and increased tumor mass in breast cancer." (PMID 34771725, 2021). "As a consequence of its ability to trigger the EGF receptors (EGFR) pathways by shedding EGFR ligands, ADAM17 activity is linked to several tumours such as colon and breast cancer development." (PMID 34362154, 2021). "An increased expression of ADAM17 in tumor-associated fibroblasts has already been described in breast cancer." (PMID 34771725, 2021). "In breast cancer patients, ADAM17 expression in tissue correlates with an increased risk for metastasis and poor survival." (PMID 34771725, 2021). "As a consequence of its capability to trigger the epidermal growth factor receptor (EGFR) pathway by shedding EGFR ligands, ADAM17 activity is associated with cancer progression of several malignancies, including colon and breast cancer." (PMID 33579029, 2021). "Genetic deletion of ADAM17 in leukocytes resulted in decreased onset of mammary tumor growth, which was associated with reduced expression of the Cox-2 within the tumor." (PMID 27738494, 2016). "Recent studies have shown that ADAM17 is highly expressed in non-small cell lung cancer, breast cancer and other malignant tumors, and is associated with the degree of malignancy." (PMID 25364437, 2014). "Although the ELISA used in this study detected both the precursor and active forms of ADAM17, a previous study found that the active form was more associated with breast cancer progression than the precursor form." (PMID 21906355, 2011). "Findings support this notion that ADAM17 is implicated in breast carcinoma progression." (PMID 38317965, 2024). "The clinical relationship of membrane ALCAM loss with progression in ovarian and breast cancer may also relate to the process of ALCAM shedding by ADAM17/TACE." (PMID 21364949, 2011). "ADAM17 may not only function in its cell-associated form but might be also released as soluble ectodomain by the action of ADAM8 resulting in a cell-associated remnant form as was recently shown in breast cancer cells." (PMID 35892600, 2022). "Key genes, such as BSG, TGFBI, and ADAM17, were already shown as having well-established roles in breast cancer biology." (PMID 41374933, 2025). "INCB7839, an inhibitor of ADAM10 and ADAM17 proteases, has undergone assessment in Phase I–II clinical trials for previously treated solid tumors and breast cancer." (PMID 38797752, 2024). "ADAM17 plays also an important role in breast cancer, where it has been shown to influence cell invasion and proliferation, but also angiogenesis and cancer cell apoptosis." (PMID 37175852, 2023). "High ADAM17 expression was related to tumor invasiveness or adverse prognosis also in hepatocellular carcinoma, breast cancer, clear-cell renal carcinoma and glioblastoma." (PMID 36140519, 2022). "Among MMPs, ADAM-17 mediated cleavage has been recognized as responsible of CD16 shedding in breast cancer." (PMID 36341402, 2022). "BB‐94 has been shown to suppress the production of soluble vasorin through inhibition of ADAM17 in MCF7 breast cancer cells." (PMID 35170203, 2022).
breast carcinoma (continued). "The A300E mAb was initially developed against the disintegrin–EGF-like domain of human ADAM17; when conjugated to doxorubicin or Pseudomonas exotoxin, it induces in vitro death of breast cancer cells in an ADAM17-dependent manner." (PMID 35158891, 2022). "More importantly, ADAM17 is contributory to the occurrence and development of cancers, including lung carcinoma, ovarian carcinoma, breast carcinoma, gastric carcinoma, and cervical carcinoma." (PMID 36466812, 2022). "In summary, the critical role of ADAM17 in breast cancer makes it a potential target for breast cancer therapy." (PMID 36466812, 2022). "Using CRISPR/Cas9 gene editing, we knocked out Adam17 expression (Adam17–/–) in the mouse breast cancer cell lines 4T1 and E0771." (PMID 35998057, 2022). "ADAM17 functions as one of the highly expressed genes in breast cancer that plays an important role in the development of breast cancer." (PMID 36466812, 2022). "Fittingly, in ADAM17-silenced breast cancer cells, p-AKT levels are likewise significantly decreased, and forced expression of ADAM17 enhanced the phosphorylation of AKT in hepatocellular carcinoma cells without affecting the expression of total AKT." (PMID 36293469, 2022). "Overexpression of ADAM17 was also seen in other cancers including breast cancer, brain tumor and colorectal cancer." (PMID 34182543, 2021). "ADAM17 contributes to the development and progression of breast cancer by significant levels of TGF-α, which plays an important role in this pathological process." (PMID 34362154, 2021). "Through this system, we identified Adam17 as the negative regulator of Procr membrane expression both in mammary epithelial cells and breast cancer cells." (PMID 34281556, 2021). "Using this system, we screened and identified Adam17 as a negative regulator of Procr protein expression in both mammary epithelial cells and breast cancer cells, suggesting potential therapeutic significance." (PMID 34281556, 2021). "Here, we studied the expression of ADAM17 on the surface of platelets in the context of breast cancer." (PMID 34208863, 2021). "ADAM17 promotes progression of breast cancer by regulating levels of TGFα, which plays a pivotal role in this pathological process." (PMID 33579029, 2021). "Among them, ADAM17 is expressed by TAMs in breast cancers and is involved in the regulation of pro-inflammatory mediators, including cytokines, such as cyclooxygenase-2." (PMID 33971970, 2021). "It is reported that ADAM17 can enhance breast cancer cells’ invasion and proliferation in vitro and promote breast cancer cell malignant phenotype." (PMID 34208863, 2021). "Genetic deletion of ADAM17 in leukocytes leads to later onset of breast cancer growth, while HLA-G is produced by tumor-infiltrating microglia in most glioblastomas." (PMID 33971970, 2021). "In a first step, we determined the expression of ADAM17 on platelets of 20 healthy donors (HD) and 79 breast cancer patients using flow cytometry." (PMID 34208863, 2021). "One of the substrates of ADAM17, nectin-4, was easier to detect in breast cancer patients with metastasis." (PMID 34182543, 2021). "Several reports have shown that members of the ADAM family are overexpressed in human cancers such as ADAM8 in human renal cell carcinomas, ADAM15 in lung carcinoma, and ADAM17 in breast cancers." (PMID 34249950, 2021). "In this study, we evaluated ADAM17 expression in platelets and found a specific downmodulation on activated platelets of breast cancer patients." (PMID 34208863, 2021). "The established CRISPR-Cas9/FACS screening system efficiently identified the regulators of membrane proteins and we identified Adam17 was the negative regulator of Procr both in mammary epithelial cells and breast cancer cells." (PMID 34281556, 2021). "Recently, studies reported the relationship between ADAM17 and certain cancers, including the esophageal squamous cell carcinoma, prostate cancer, breast cancer, colorectal cancer, and stomach cancer." (PMID 32610677, 2020).
breast carcinoma (continued). "ADAM12 is participated in TGF-β mediated EMT in breast cancer, while ADAM17 induces EMT in colorectal cancer via Notch signaling pathway." (PMID 32637415, 2020). "An increasing number of studies reported that ADAM17 was overexpression in tumors, including the esophageal squamous cell carcinoma, stomach cancer, breast cancer, prostate cancer, colorectal cancer, and others." (PMID 32610677, 2020). "The expression and activity of ADAM17 increase under some pathological conditions such as breast cancer and lung cancer." (PMID 32976115, 2020). "Similar to the DLD‐1 cell system, we removed endogenous ADAM17 using CRISPR/Cas9 from the mouse breast cancer cell line 4T1 and exogenously expressed the different ADAM17 variants (and EV4I and J)." (PMID 32400009, 2020). "Interrupting ErbB receptor transactivation by a combined inhibitor of ADAM10 and ADAM17 reduced non-small-lung-cancer-cell formation, subcutaneous tumor growth, and breast cancer and fibroplasia." (PMID 28260841, 2017). "Mechanistically, ADAM17 on breast cancer cells has been found to cleave and release epidermal growth factor (EGF) family members from the cell surface, which then act through EGF receptor (EGFR) to promote tumor cell proliferation and invasion." (PMID 27738494, 2016). "ADAM10 and ADAM17 have been shown to contribute to the acquired drug resistance of HER2-positive breast cancer in response to trastuzumab." (PMID 28442704, 2016). "Examination of ADAM17 and Cox-2 in human breast cancers using publically available databases demonstrates a link between increased expression levels of these factors and reduced relapse free survival, particularly in estrogen receptor (ER)-negative tumors." (PMID 27738494, 2016). "ADAM17 contributes to breast cancer growth and progression through the cleavage and shedding of key soluble factors, including members of the EGF ligand family." (PMID 27738494, 2016). "Inhibition of ADAM10 activity or expression resulted in an increase of trastuzumab efficacy, which suggested that ADAM10 and ADAM17 are tractable targets for HER2-positive trastuzumab-resistant breast cancer." (PMID 28442704, 2016). "p110 CUX1 overexpression in the breast carcinoma cell line Hs578T also increased the expression of ADAM17 and HEY1, a downstream target of NOTCH 50, whereas downregulation of p110 CUX1 in the same cells decreased the NOTCH signalling." (PMID 27941799, 2016). "We demonstrate here that ADAM17 is expressed by leukocytes, including macrophages, in mammary tumors and that genetic deletion of ADAM17 specifically in leukocytes leads to reduced formation of polyoma middle T (PyMT)-derived mammary tumors." (PMID 27738494, 2016). "In summary, our findings implicate ADAM17 as an important regulator of leukocyte function during mammary tumor formation." (PMID 27738494, 2016). "As described here, our findings define ADAM17 as an important regulator of Cox-2 expression in macrophages in vitro and in mammary tumors in vivo." (PMID 27738494, 2016). "They found that ADAM17 mRNA expression in breast cancer tissue was positively correlated with the number of lymph node metastasis." (PMID 25351873, 2015). "Recent studies have shown an increase in the expression and activity of ADAM17 in a number of human tumor tissues, including breast cancer, lung cancer, gastric cancer and liver cancer." (PMID 25351873, 2015). "In contrast, here we showed that the major forms of ADAM17 were inhibited over time in lapatinib-treated parental HER2+ breast cancer cell lines (compare 1-hour and 24-hour treatments)." (PMID 24044505, 2013). "Overexpression of ADAM17 in MCF-7 breast cancer cells up-regulated, while ADAM17 silencing in MDA-MB-435 cell line down-regulated cell proliferation and invasiveness in vitro." (PMID 23251384, 2012).